RETN (resistin)
Diseases named in the same sentence as RETN in open-access papers (continued):
Sharing a sentence is not in itself a finding about the gene and the disease.
psoriasis (continued). "Previous studies have reported a correlation between increases in the expression of TNF-α, resistin, and visfatin in a variety of inflammatory diseases including rheumatoid arthritis, inflammatory bowel disease, and psoriasis." (PMID 28018676, 2016). "In this study we evaluated the significance of serum resistin levels in psoriasis patients using a meta-analysis approach." (PMID 25980409, 2015). "Taken together, the present study revealed higher serum resistin levels in psoriasis patients compared to healthy controls, indicating that elevated serum resistin levels strongly correlate with psoriasis progression." (PMID 25980409, 2015). "Nevertheless, due to the limitations in this study, it is necessary to extend our analysis to a larger population to confirm the relationship between serum resistin levels and psoriasis." (PMID 25980409, 2015). "In the present meta-analysis, we examined the relationship between serum levels of resistin and psoriasis." (PMID 25980409, 2015). "Subgroup analysis showed that higher serum resistin levels were observed in both Asians and Caucasian psoriasis patients, compared to their healthy counterparts, suggesting no detectable racial differences in our analysis." (PMID 25980409, 2015). "Recent study shows that resistin plays a predominant role in the pathogenesis of psoriasis, particularly in obese patients." (PMID 25980409, 2015). "In addition, resistin may play a role in Foxp3+ regulatory T-cell (Treg) deficiency in psoriasis." (PMID 25980409, 2015). "Based on our results, we conclude that serum resistin level in psoriasis patients is higher than healthy controls, and raises the possibility that elevated serum resistin levels may be a novel diagnostic marker in psoriasis and may predict the occurrence of co-morbidities in psoriasis patients." (PMID 25980409, 2015). "All articles were case–control studies reporting the relationship between serum resistin levels and psoriasis in Asian (5 studies) and Caucasian populations (4 studies)." (PMID 25980409, 2015). "Serum levels of resistin, another adipokine, were found to correlate with disease severity in psoriasis." (PMID 23843781, 2013). "Corbetta and co-workers showed that increased serum resistin levels in untreated psoriasis patients were normalized after 1 and 3 months of acitretin therapy." (PMID 23144698, 2012). "In humans, a small study on patients with psoriasis showed normalization of the increased resistin serum levels after treatment with retinoid therapy." (PMID 17479165, 2007). "Retinoic acid, the acid form of vitamin A, inhibited the expression of resistin in mice and reduced the higher resistin levels of ten men affected by psoriasis." (PMID 17479165, 2007). "The aim of this study was to evaluate the inflammatory potential and the association of psoriasis with metabolic and cardiovascular risk by analyzing serum concentrations of homocysteine, adiponectin, resistin, leptin, and pentraxin 3 in pediatric patients with psoriasis." (PMID 40095687, 2025). "Increased resistin levels were significantly associated with both HSV (p = 0.002) and HIV (p = 0.018) positivity, in which it is proposed that these viral infections can influence the regulation of resistin (a pro-inflammatory cytokine) and worsen psoriasis exacerbation." (PMID 40724556, 2025). "A positive correlation was observed between resistin serum concentration and psoriasis severity." (PMID 40095687, 2025). "Elevated resistin levels in adult psoriasis patients have been documented." (PMID 40095687, 2025). "Serums with active viral co-infection can be analyzed for resistin, as well as clinical documentation of viral load, as resistin levels can be increased as the viral load increases, resulting in a worsening of physical symptomology (i.e., psoriasis flare)." (PMID 40724556, 2025). "They found that resistin levels were higher in more severe cases of psoriasis." (PMID 40095687, 2025).
psoriasis (continued). "Given the potential link between psoriasis and viral infection, and the significance of inflammatory markers like resistin, CRP, and CMIT in suggesting systemic inflammation, it is critical to explore the incidence of viral infection in psoriasis patients with elevated levels of these markers." (PMID 40724556, 2025). "Conversely, resistin, a pro-inflammatory adipocytokine associated with Th1/Th17 immune responses, was significantly elevated by TNF-α alone or in combination with IL-17, supporting its role in exacerbating inflammatory pathways relevant to psoriasis." (PMID 39769200, 2024). "Previous studies suggest that adiponectin may have anti-inflammatory effects in psoriasis, slowing the development of the disease, while leptin and resistin may increase inflammation, exacerbating the symptoms of psoriasis." (PMID 36675592, 2023). "In addition, resistin can inhibit the proliferation of Foxp3+ regulatory T (Treg) cells in psoriasis." (PMID 36675592, 2023). "It has also been described that the major adipokines, leptin, resistin, and adiponectin, may be involved in the pathogenesis of psoriasis." (PMID 36675592, 2023). "Then we analysed the correlations between plasma concentrations of adiponectin, leptin, and resistin, and parameters of psoriasis activity using the Dermatology Life Quality Index (DLQI), Psoriasis Activity Severity Index (PASI), and Body Surface Area (BSA) index." (PMID 36675592, 2023). "The most studied adipokines in psoriasis are adiponectin, leptin, and resistin." (PMID 37895330, 2023). "Another study with 47 psoriasis patients, serum levels of IL-6, TNF-α and proinflammatory adipocytokines (leptin, resistin and visfatin) were higher in psoriasis patients and serum adiponectin (an anti-inflammatory cytokine) was lower in psoriasis patients relative to healthy controls." (PMID 37681925, 2023). "Interestingly, recent studies have started to investigate the role of resistin in the pathogenesis of psoriasis." (PMID 37047363, 2023). "Since the inhibition of these cytokines might alleviate the development of psoriasis, the precise role of resistin in psoriasis is yet to be discovered." (PMID 37047363, 2023). "Secondly, patients with psoriasis present increased levels of plasma resistin." (PMID 37047363, 2023). "Disturbances in levels of adipokines (e.g. decreased levels of adiponectin and omentin and increased levels of leptin and resistin) may play a role in increasing the prevalence of cardiovascular disease in psoriasis patients." (PMID 36202827, 2022). "Authors concluded that improvement of adiponectin, leptin and resistin serum concentrations are linked to effective psoriasis treatment, and this effect is not specific to any type of the therapy." (PMID 33927259, 2021). "Importantly, the correlation with resistin, myeloperoxidase, and the effect of psoriasis treatment on the studied parameters is preliminary and was performed on a significantly smaller cohort than the other analyses." (PMID 31936662, 2020). "Concerning the role of resistin in psoriasis, in addition to its effect on proinflammatory cytokine production, its connection with proprotein convertase subtilisin/kexin 9 (PCSK9) may represent another key mechanism." (PMID 31824416, 2019). "Further, the plasma levels of leptin and resistin are related to the severity of psoriasis." (PMID 31275060, 2019). "In conclusion, serum levels of TNF-α, IFN-γ, IL-2, IL-6, IL-8, IL-18, IL-22, chemerin, lipocalin-2, resistin, sE-selectin, fibrinogen and C3 were significantly elevated and serum level of adiponectin was significantly decreased in psoriasis patients compared to healthy individuals." (PMID 29416693, 2018). "This could be explained by the concept of “psoriatic march” regarding psoriasis as a chronic systemic inflammatory disorder, with not only the classical markers for systemic inflammation, but also elevated resistin and leptin levels." (PMID 30011841, 2018).
psoriasis (continued). "Subgroup analysis based on ethnicity showed that, compared to the healthy controls, serum resistin levels were markedly higher in psoriasis patients in both Asian and Caucasian populations (Asians: SMD = 3.27, 95%CI = 1.62 ~ 4.91, P < 0.001; Caucasians: SMD = 0.91, 95%CI = 0.28 ~ 1.54, P < 0.001)." (PMID 25980409, 2015). "Firstly, our study could not access all available sources that reported data related to resistin and psoriasis due to language limitations." (PMID 25980409, 2015). "Accordingly, multiple studies proposed that serum level of resistin may be effective for predicting the presence of psoriasis, but other studies showed contradictory results." (PMID 25980409, 2015). "In order to consider other factors that may affect the link between serum resistin level and psoriasis, we performed a stratified analysis based on ethnicity." (PMID 25980409, 2015). "A total of 9 studies reported serum resistin levels in psoriasis patients." (PMID 25980409, 2015). "Subgroup analysis based on ethnicity revealed that serum resistin levels were significantly higher in psoriasis patients, compared to healthy controls, in both Asians and Caucasians (Asians: SMD = 3.27, 95%CI = 1.62 ~ 4.91, P < 0.001; Caucasians: SMD = 0.91, 95%CI = 0.28 ~ 1.54, P < 0.001)." (PMID 25980409, 2015). "However, when the sample with psoriasis patients was studied, the observed values of resistin levels did not associate with the degree of skin involvement nor with the presence or disease activity in those with psoriatic arthritis." (PMID 37355349, 2023). "In addition to psoriasis treatment monitoring by imaging techniques, as well as C-reactive protein, erythrocyte sedimentation rate, fibrinogen, zinc, and copper levels, resistin could also be a valuable predictive marker." (PMID 37895330, 2023). "Finally, resistin is an adipokine and a potential biomarker in psoriasis pathogenesis and obesity." (PMID 35886846, 2022). "Therefore, it was considered that resistin might be a potential biomarker for diagnosis and prognosis in psoriasis patients." (PMID 33927259, 2021). "As a result, resistin may act as an activator of PCSK9 in the pathogenesis of psoriasis." (PMID 31824416, 2019). "Interestingly, high serum resistin levels are also observed in psoriasis patients." (PMID 25980409, 2015). "Therefore, resistin level may be useful as a biomarker for diagnosis of psoriasis and to adjust the treatment regimen during fluctuating severity of the disease." (PMID 25980409, 2015). "The results of our meta-analysis revealed that higher serum resistin levels positively correlated with psoriasis disease progression, indicating that resistin might be a potential biomarker for diagnosis and prognosis in psoriasis patients." (PMID 25980409, 2015). "Induction of CXCL8 and TNF-α by resistin in monocytes population in blood is also linked with psoriasis pathophysiology and TNF-α stimulates keratinocyte proliferation and T cells recruitment to the skin, thus a close relationship between resistin and TNF-α-mediated inflammation exists in psoriasis." (PMID 25980409, 2015). "Therefore, serum resistin level could be a valuable biomarker in evaluating the clinical status of psoriasis patients." (PMID 25980409, 2015). "Furthermore, resistin may contribute to the dysfunction of Foxp3+ Treg cells by impairing their tolerance to self-antigens, which exacerbates the autoimmune response and facilitates psoriasis development." (PMID 40724556, 2025). "Adipose tissue is a source of various proinflammatory cytokines, including adiponectin, leptin, resistin, TNF-α, and IL-6, participating in the pathogenesis of both psoriasis and non-alcoholic fatty liver disease (NFLD)." (PMID 41226807, 2025). "In fact, studies have shown that patients with psoriasis tend to have higher serum levels of TNF-α, IL-6, and resistin." (PMID 40740781, 2025).
psoriasis (continued). "Understanding how resistin interacts with and affects viral infections can provide additional clarity into how viral triggers, such as HSV and HIV, influence psoriasis symptoms and disease trajectory." (PMID 40724556, 2025). "In patients with psoriasis, there is an imbalance between the levels of pro- and anti-inflammatory adipokines (TNF-α, IL-6, leptin, resistin, and vifastin which increases, and adiponectin which decreases)." (PMID 38473907, 2024). "A correlation between serum resistin and PASI score was also reported, in which more severe cases of psoriasis had higher resistin levels than those with lower PASI scores." (PMID 37546687, 2023). "Interestingly, increased resistin levels are closely associated with rheumatoid arthritis, systemic lupus erythematosus, psoriasis, and other autoimmune diseases, suggesting that resistin may be a useful marker of systemic inflammatory status in autoimmune diseases." (PMID 36686437, 2022). "In conclusion, observed inflammatory and anti-inflammatory markers (CRP, adiponectin, leptin, resistin, and Lp-PLA2) are involved in both pathogenesis of MS and pathogenesis of psoriasis." (PMID 28097156, 2016). "One unexpected finding was the lack of correlation between resistin levels and cIMT, even though cIMT was higher in psoriasis patients than controls." (PMID 37355349, 2023). "Moreover, there’s a significant correlation between the elevated plasma resistin and DLQI scores in psoriasis patients." (PMID 38035065, 2023). "For example, levels of leptin and resistin are elevated in obese individuals with psoriasis compared to those without the condition." (PMID 37047363, 2023). "The aim of the study was to investigate the influence of 36-month therapy with TNF-α inhibitors (adalimumab, etanercept, infliximab) on the levels of adipokines (resistin, adiponectin, leptin) and lipids (TG, cholesterol, LDL, HDL) in 37 psoriasis patients and 30 healthy controls." (PMID 33927259, 2021). "Importantly, SGs were found to express leptin, resistin, visfatin and SERPINE1 in lesional skin samples of patients with psoriasis." (PMID 33260746, 2020). "Chemerin was linearly correlated to CRP and resistin, but not with psoriasis severity measured with PASI or body surface area (BSA)." (PMID 31275060, 2019). "In this sense, we have previously published that, in nondiabetic patients with moderate-to-severe psoriasis, leptin correlates with some metabolic syndrome features, whilst resistin correlates with inflammation and disease severity." (PMID 27293954, 2016). "The remaining 25 studies were reexamined and additional 16 studies were excluded, out of which 2 was not case–control studies, 5 were not relevant to resistin, 7 were not relevant to psoriasis and 2 contained insufficient data." (PMID 25980409, 2015). "This relationship was independent from changes in other metabolic/inflammatory parameters, in line with the absence of correlations between tumor necrosis factor and resistin changes observed in males with psoriasis who received retinoid treatment." (PMID 17479165, 2007). "Accordingly, the reduction in resistin levels was maintained 3 mo after retinoid treatment in males with psoriasis, unlike the transient effect found by the authors on insulin sensitivity." (PMID 17479165, 2007). "Consequently, resistin has a strong link with TNF-α, a major inflammatory mediator in psoriasis." (PMID 40724556, 2025). "Besides, we have also found that antitumor necrosis factor-α (anti-TNF-α) agents may improve insulin resistance in patients with moderate-to-severe psoriasis, although no significant changes in serum leptin or resistin concentrations after 6 months of adalimumab therapy were found." (PMID 27293954, 2016).
rheumatoid arthritis (51 papers, 2006 to 2025). A chronic, systemic autoimmune disorder characterized by inflammation in the synovial membranes and articular surfaces. "Inflammation is a hyperresistinemic state and several inflammatory diseases, including endotoxemia, rheumatoid arthritis, and inflammatory bowel disease, among others, are associated with increased levels of circulating resistin in humans." (PMID 35011183, 2021). "Serum resistin concentrations were also directly associated with markers of inflammation in obese people and post-menopausal women with rheumatoid arthritis." (PMID 30205427, 2018). "Although resistin was initially associated with metabolic disorders, increased levels of resistin and its positive correlation with inflammatory markers and disease activity have been previously demonstrated in patients with rheumatoid arthritis (RA)." (PMID 22577940, 2012). "It is worth underlining that resistin has been suggested to be involved in vascular inflammation and dysfunction, and its involvement in rheumatoid arthritis has been generally accepted." (PMID 19196461, 2009). "We have previously reported that adipokines, especially resistin, may be associated with inflammatory processes in rheumatoid arthritis (RA), Kawasaki disease, and other systemic autoimmune diseases." (PMID 27649254, 2016). "Despite having a significant contribution in the maintenance of energy homeostasis, resistin may exert a larger impact on inflammatory processes—resistin has been linked to rheumatoid arthritis, psoriatic arthritis and systemic lupus erythematosus and is suspected to be involved in SSc pathogenesis." (PMID 30806766, 2019). "There is evidence that resistin has proinflammatory properties and is abundant in inflammatory diseases (for instance, rheumatoid arthritis (RA) and Crohn disease) and also is associated with inflammatory markers in several different populations." (PMID 18234104, 2008). "Adiponectin, leptin, and resistin are thought to be involved in the pathogenesis of rheumatoid arthritis (RA)." (PMID 37294817, 2023). "Adiponectin, leptin, and resistin are cytokines produced by the adipose tissue, so called adipokines, and they are thought to be involved in the pathogenesis of rheumatoid arthritis (RA), a chronic inflammatory disease." (PMID 37294817, 2023). "It complies with the elevated serum resistin level in other chronic systemic inflammatory diseases, including rheumatoid arthritis and systemic lupus erythematosus." (PMID 31667578, 2020). "This is in contrast to several studies have reported elevated resistin levels in various inflammation-related diseases like rheumatoid arthritis, inflammatory bowel disease and failed renal allografts." (PMID 31856765, 2019). "We have previously found resistin as a contributing factor and biomarker involved in osteoarthritis, rheumatoid arthritis, inflammatory lung diseases and ischemia-reperfusion syndrome associated with cardiac surgery." (PMID 30517161, 2018). "In rheumatoid arthritis, resistin has been shown to accumulate within inflamed joints, and to correlate with the degree of inflammation and the expression of inflammatory cytokines including TNF-α, IL-1β and IL-6." (PMID 28642544, 2017). "Previous studies have shown that resistin expression is increased in various chronic inflammatory conditions such as rheumatoid arthritis, chronic kidney diseases, diabetic retinopathy, coronary heart diseases, and periodontitis." (PMID 25404641, 2015). "In human studies, synovial fluid from patients with rheumatoid arthritis (RA) showed significantly higher level of resistin compared with control samples." (PMID 24692844, 2014). "Several adipokines other than RBP4 and including adiponectin, leptin and resistin can participate importantly in the pathophysiology of rheumatoid arthritis (RA), a prototypic inflammatory disease." (PMID 24651174, 2014).